CD4 (CD4 molecule)
Diseases named in the same sentence as CD4 in open-access papers (continued):
Sharing a sentence is not in itself a finding about the gene and the disease.
infection (continued). "A decreased thymic output of naïve T cells was observed in both CD4 and CD8 compartment in ESRD patients and was associated with severe infection episode and cardiovascular events in these patients." (PMID 32660510, 2020). "The cluster A epitopes become exposed upon Env triggering with cell surface CD4 and, therefore, are available for antibody recognition during the viral entry process in active infection of the CD4+ T cell population and in cell-to-cell spread (1, 6, –, 9)." (PMID 32605979, 2020). "We developed a dual-color CD4/CD8 co-culture assay to examine the effect of autologous TCR-activated CD8+ T cells from HIV-uninfected healthy subjects in modulating the ex-vivo infection of CD4+ T cells." (PMID 32941545, 2020). "In wild-type mice, CD4 T cells began production 3 days after infection and peaked at day 7, when parasite burden had been reduced to the limit of detection." (PMID 32669460, 2020). "In early infection, an understanding of the mechanism of T-cell evasion, including impaired or misregulated dendritic cell maturation and delayed priming of CD4+ T cells, is essential in the design of vaccines for successful antigen activation of CD4+ T cells." (PMID 33105734, 2020). "Cis-infection is the process whereby productively-infected DCs produce virus progeny, which augments the amount of virions available to infect CD4+ T lymphocytes." (PMID 32181159, 2020). "Upon vaccination but prior to infection, CD4+CD44+ T-cell numbers generally increased in all organs, when compared to the numbers in naïve mice." (PMID 32545304, 2020). "According to the cytokine environment, naive CD4+ T lymphocytes can differentiate into a protective subset (Th1) or a Th2 cell subset, which favors the progress of infection." (PMID 32760744, 2020). "African green monkeys (AGMs) are natural hosts of SIV that postthymically downregulate CD4 to maintain a large population of CD4–CD8aa+ virus-resistant cells with Th functionality, which can result in AGMs becoming apparently cured of SIVagm infection." (PMID 32841214, 2020). "This tightly reconciles with the reported expansion of CD4+ Tregs within the periparasitic environment during AE and the debilitating role of this cell type on the host ability to control the infection." (PMID 32457746, 2020). "Our work shows that infected fish at 15°C presented the overexpression of STAT1, MHCII, CD4, IgT, and IgM transcripts, suggesting that the infection triggered a CD4+ T-cells response and a humoral response." (PMID 32695119, 2020). "Temporal neutralization of IL-4 revealed that acute IL-4 produced within the first days of infection is critical for not only programming IL-4–producing Th2 CD4+ T cells, but for promoting IFN-γ produced by CD8+ T cells." (PMID 32948646, 2020). "The frequency of CD161+ cells within the CD4+ T compartment was reduced at the first available time point post-infection in AHI, corresponding to peak HIV-1 VL, and at all subsequent time points measured compared to pre-infection." (PMID 33322496, 2020). "The presence of endogenous CCR5 on CD8+ T cells makes these otherwise HIV-refractory cell types potentially vulnerable to infection via the transduced CD4 moiety, thus compromising their function and viability." (PMID 32523897, 2020). "Maldini and colleagues investigated the therapeutic utility of gene-engineered, HIV-resistant/specific CD4+ T cells to directly combat infection and restore T cell help that is lost due to HIV-mediated destruction of endogenous CD4+ T cells." (PMID 32454027, 2020). "In the early stages of infection, this targeting is less efficient, as the concentration for virus or CD4+ T cells is often very low at the infection sites." (PMID 32326128, 2020). "The role of CXCR3 in T cell migration has been demonstrated during infection by Toxoplasma gondii: CXCR3+ CD4+ T migrated into infected tissues and controlled the infection." (PMID 32574175, 2020).
infection (continued). "Those children having low CD4 cell count at baseline are exposed to a different infection that leads to different complications and finally leads to death." (PMID 32973396, 2020). "The significantly higher activated CD4+ and Th17 cells in secondary infection compared with primary infection was revealed at convalescent time." (PMID 33072068, 2020). "To determine how long the effect of stress persists, we compared the gene expression of T-bet and GATA-3 or secretion of IFN-γ and IL-4 by CD4+ T cells at two- or 11-days post-infection." (PMID 32413046, 2020). "MDV, as a highly cell-associated alphaherpesvirus, has some similarity with human alphaherpesvirus in certain aspects such as infection of APCs or CD4+ T cells, cell-to-cell transmission, and reactivation after a period of latency." (PMID 32080753, 2020). "Although epitope-specific CD4+ T cells against RSV were rare even in the airway before infection, the frequency of RSV-specific CD4+ T cells was significantly higher in BAL than blood at rest (P = 0.0001)." (PMID 31815739, 2020). "As known, the depletion of CD4+ T lymphocytes and the associated impairment of the immune system make HIV patients more vulnerable to acquiring other infections and to developing more severe clinical manifestations." (PMID 32079128, 2020). "Although virtually all HIV strains use CD4, the viruses that usually mediate primary infections use CCR5 as co-receptors and infect CCR5 expressing cells (so called R5 HIVs)." (PMID 31863725, 2020). "In line with that, immune CD4+ T cells act on MΦ in the infection with R. typhi and activate the bactericidal activity of these cells via the release of IFNγ and TNFα." (PMID 33091016, 2020). "It is known that the inflammatory cells are recruited towards the site of infection, in which T-cells, particularly CD4+ cells, are predominantly observed in bovine mastitis." (PMID 33202860, 2020). "CD4+ cells showed low expression of this marker at the early phase of infection, having progressively increased over time, indicating that the exhaustion of these cells occurs as the disease progresses." (PMID 33193331, 2020). "In contrast to the observed in primary infection, it is well established that both Th1 and Th17 CD4+ T cells are required to mediate protection against S. aureus in different models of re-infection in mice." (PMID 33291260, 2020). "We also showed that both influenza A and B infections elicited a significant increase in polyfunctional CD4 + T-cells, which are considered to be a good correlate of the quality of the T-cell response." (PMID 32572168, 2020). "Phenotypic analysis of lymphocyte activation status in CL infection revealed significant increase of CD4+ T cells more prominent in acute phase of the infection." (PMID 32656269, 2020). "In early infection, a decrease in lymphocyte counts was observed in the severe group, and this was characterised by a dramatic loss of NK cells, B cells, CD3+, CD4+, and CD8+ T cells." (PMID 32922406, 2020). "Longitudinal tracking of CD4+ T cell frequencies in peripheral blood revealed an average decline of 8.9% (standard deviation [SD], ±4.9) from the day of infection to ART initiation at 8 wpi." (PMID 33087463, 2020). "In contrast, all control mice survived (naïve, CnH99-infection alone, and CD4+ T cell transfer alone) in the experiment period." (PMID 33133067, 2020). "Retrospectively, the patient’s CD4 count was 44 cells/μL at the time of infection, thus emphasizing the importance of implementing immune monitoring protocols to guide the duration of antimicrobial prophylaxis in these patients." (PMID 32759935, 2020). "By producing single cycle viruses in YTHDF3 deficient cells with and without YTHDF3 complementation, we show that virion-incorporated YTHDF3 is sufficient to limit infection of CD4+ T cells by acting at the step of reverse transcription." (PMID 32053707, 2020).
infection (continued). "Uptake into DCs using this method not only allows efficient trans-infection to target CD4+ T cells but also evades detection by the immune system, the importance of which was shown in vivo using a humanized mouse model." (PMID 32075937, 2020). "Very few CD4+ or CD8+ TRM cells were present in CLNs of SINV-infected mice at any time after infection." (PMID 31963302, 2020). "Suppose the estimated number of infections in the ith year before t0 is mi (using the CD4 depletion model)." (PMID 31964392, 2020). "In contrast, individuals that acquired HIV had a significant inverse association between the pre-infection levels of CD4 T cells co-expressing CCR5 and CD161 pre-infection and the CD4 nadir (rho = −0.68, p = 0.04)." (PMID 33322496, 2020). "SJL mice with elevated numbers of the initial virus-reactive CD4+ T cells developed more severe and rapid clinical symptoms after infection with high viral doses (1 × 106 and 5 × 106 PFU)." (PMID 33086489, 2020). "Previous work examining the role of T-bet in STm infection has shown that splenic CD4+ T cells from T-bet−/− mice exhibit defective production of IFN-γ postinfection." (PMID 32591391, 2020). "In the majority of cases, CD4+ T cells will control the bacteria from further infection; however, in some cases, the infection can reactivate and develop to an acute, chronic, or extrapulmonary infection." (PMID 33027958, 2020). "Potential similarities are also seen with a population of IL-21-producing CD4+ T cells in the CNS after infection with mouse polyoma virus (MuPyV)." (PMID 33120989, 2020). "Ex vivo S47 mouse splenocytes infected with Lm show greater numbers of CD25+, CD4+, FoxP3-Hi Tregs, 24 h post infection." (PMID 31980600, 2020). "Antiretroviral therapy (ART) cannot cure HIV or eliminate infection from long-lived and proliferating latently infected CD4+ T cells." (PMID 32109259, 2020). "The results of the RT assays performed at 5, 7, and 9 days post-infection showed that NU7441 effectively repressed HIV replication in primary CD4+ T cells in a dose-dependent fashion." (PMID 32133046, 2020). "The outcome of infection is mainly dependent on the activation of one of the two subsets of CD4+ T cells, Th1 and Th2 cytokines, that activate macrophages and DCs." (PMID 32656269, 2020). "In the spleen, the percentage of CD4+ CD8+ double-positive T cells in the infection group declined at 42 DPI (p < 0.05) compared with the control group, but there is no obvious difference at the other test index." (PMID 31963363, 2020). "By matching the high-dimensional CyTOF profile of each HIV-infected cell to an ‘atlas’ of uninfected CD4+ T cells from the same donor, we are able to predict the phenotype of the original cell preferentially targeted for infection." (PMID 32452381, 2020). "CD4+ T cells indirectly control infection by enhancing B and CD8+ T cell activation, memory to control recurring pathogen, and production of inflammatory and anti-viral cytokines." (PMID 33072068, 2020). "These IFN-γ+IL-21+ hybrid Th1/Tfh cells are reminiscent of CD4 T cells identified in other persistent infections, leading us to investigate the role of continuing infection in their generation, and to identify molecular mechanisms regulating their generation." (PMID 32634740, 2020). "High CD4+ T-cell and CD8+ T cell IFN-γ responses during early infection in Cynomolgus macaques were associated with better long-term viral control." (PMID 32528466, 2020). "tSNE analysis revealed an increase in the level of PD-1 at weeks 2 and 3 post-infection, overlapping with spatial regions corresponding to both CD4+ T and CD8+ T cells." (PMID 33247138, 2020). "CD4+ T cells, acting through IL-22, play a crucial role as a defense mechanism against Cr infection." (PMID 32230738, 2020). "While CD4+ T cells from unstimulated PBMCs are poorly permissive to productive infection by HIV, a fraction of these cells within tonsils are efficiently infected in the absence of ex vivo stimulation." (PMID 32452381, 2020).
infection (continued). "These and other examples clearly show that, depending on the vaccination approach and the utilized infection model, different CD4+ effector T cell subsets can confer protection against S. aureus." (PMID 32849537, 2020). "CD4 T cells normally play a minor role in control of T. gondii infection in immune sufficient hosts, where infections are usually well contained and largely asymptomatic." (PMID 32669460, 2020). "In contrast to CD8+ T cells, where co-inhibitory receptor expression was significantly lower throughout the duration of the chronic infection, PD-1 downregulation was only transient on CD4+ T cells and occurred during early stages of the infection." (PMID 32152316, 2020). "Despite efficient BAFF blockade, counts (blood) and proportions (spleen and terminal ileum) of total CD4+ T-cells at 28 dpi as well as the dynamics of pVL over the 1st month of infection were comparable in BR3-Fc-treated and Placebo macaques." (PMID 32194549, 2020). "STM infection has been more intensively studied in mice where CD4+ T cells were shown to have a dominant role in primary clearance of infection." (PMID 33584671, 2020). "Upon infection with LOAd viruses, both CD4+ and CD8+ T cells were able to highly upregulate CD107a as well as the activation marker CD69 in co-culture with MM cells." (PMID 32355275, 2020). "The rTsTPX2-activated macrophages (MrTsTPX2) were tested for polarization, their ability to evoke naïve CD4+ T cells, and resistance to the larval infection after adoptive transfer in BALB/c mice." (PMID 33072069, 2020). "CD4+ and CD8+ T-cells are likely targeted by DENV, particularly during secondary infection when serotypes cross-react with bystander CD4+ and CD8+ T cells." (PMID 32429962, 2020). "The only consistently recognized CD4+ Trm cell marker is CD69, and the phenotypic characteristics of CD4+ Trm cells over the course of infection are unclear." (PMID 31815739, 2020). "We find that HIV significantly remodels both endometrial cells and PBMCs following infection and that remodeling involves downregulation of cell-surface CD4, as expected, but also downregulation of other components of the TCR complex." (PMID 32452381, 2020). "CD4+ T cells, as the major component of adaptive immunity, protect humans from infection, and have a declining ability to respond with increasing age." (PMID 33269101, 2020). "In cells with high CD4 levels (~450,000 molecules/cell), efficient infection by macrophage-tropic HIV was supported even for low CCR5 levels (700–2000 molecules/cell)." (PMID 31863725, 2020). "The percentage of NK cells and CD4+ T cells in the blood and spleen was identical at steady state for the two groups and splenic CD4+ T cells followed similar kinetics from day 2 to day 8 post-infection." (PMID 33343572, 2020). "We next focused our analysis on three parameters (viral load, CD4 count, and duration of infection) to identify factors driving bnAb induction." (PMID 32879304, 2020). "Consistent with previously published data for P. chabaudi, CD4+ splenic T-effectors (TE) reached maximum levels of expansion in the acute phase of infection, increasing by up to 10-fold." (PMID 33329568, 2020). "Our results showed that CD4+ T cells increased after infection and peaked at 3 dpi, which was similar to the results obtained by previous studies." (PMID 32085808, 2020). "We found that the 2W-specific CD4+ T cells expanded more rapidly following secondary infection, reaching near peak levels as early as 3 dpi in the SLOs, blood, and liver." (PMID 32983171, 2020). "Outer membrane (OM) proteins of A. marginale have been shown to induce homologous protection against infection, characterized by antigen specific CD4+ T cells and IgG2 production in calves." (PMID 33363134, 2020). "Human immunodeficiency virus (HIV) is an infection that attacks the body’s immune system, specifically the white blood cells called CD4 cells." (PMID 32874668, 2020).
infection (continued). "CD161+ CD4+ T cells are also depleted from peripheral blood during CHI, and are susceptible to infection by both CCR5 and C-X-C chemokine receptor (CXCR) 4-tropic viruses." (PMID 33322496, 2020). "The sample included 30 treatment-naive patients classified into three groups based on infection duration (> 6 years), CD4+TC count and viral load: (i) 2 elite controllers (ECs), (ii) 7 viremia controllers (VCs) and (iii) 21 nonviremia controllers (NVCs)." (PMID 32711474, 2020). "We were able to demonstrate that multiple administrations of hACE2-encoding mRNA can be used to detect enhanced CD4+ and CD8+ T cell responses to the structural proteins of SARS-CoV-2 during a prime and boost infection." (PMID 33326500, 2020). "The other appears in the late stage of infection and is closely related to CD4+ and CD8+ T cells that are essential for the establishment and maintenance of the second chemotactic gradient." (PMID 32477330, 2020). "Overall, our results indicate that FTY720 not only reduces productive infection but that the effect is carried over into a reduced incidence of latently infected primary CD4 T cells." (PMID 32790802, 2020). "One group found that MR binds HIV on the plasma membrane of macrophages and transfers virions to CD4+ T cells, a process known as trans-infection." (PMID 32726944, 2020). "Evaluation of infection-induced changes in CD4 T cell differentiation at Day 7 revealed a strong phenotypic shift to Th1 effectors (CXCR3+), Th1 polarized Tfh cells (CXCR3 + CXCR5+) and Th1 Th17 (CXCR3 + CCR6+) CD4 T cells." (PMID 32818217, 2020). "They act via several mechanisms of action to reduce the severity of infection and rate of infectivity of the virus by decreasing the viral load while increasing CD4 counts." (PMID 33193964, 2020). "DNA methylation changes were identified already in primary infection and were more abundant in lymph node than blood CD4 + T cells." (PMID 33298174, 2020). "Infection with the retrovirus HTLV-1 leads to the development of either CD4+CD25+ leukemia/lymphoma (ATLL) or a demyelinating neuroinflammatory disease (HAM/TSP) in a subset of infected individuals." (PMID 33362245, 2020). "Its synthesis is upregulated during infection to simulate the adaptive immune response by inducing differentiation of activated B cells and CD4+ T cells." (PMID 33488586, 2020). "In most HIV-infected persons, the natural history of untreated infection is one of sustained viremia, progressive CD4 T cell depletion with resultant morbidity and mortality." (PMID 32582872, 2020). "Regarding CD4+ T cells, these cells comprise a heterogenous group of T cells that differentiate into specific effector roles based on the infection type and cytokine milieu." (PMID 32756443, 2020). "Suppose the estimated number of infections in the ith year after t0 is ni (using the CD4+ T-cell depletion model), where i=1,2,⋯,N, and the time of infection for each case is DIj,j=1,2,⋯,ni." (PMID 31964392, 2020). "Following initial infection of target cells, (h) local viral amplification occurs mainly in CD4+ T cells prior to migration of (i) free virus and/or (j) infected cells to regional lymph nodes." (PMID 33212766, 2020). "Cultured CD4+ T cells drift from their original transcriptional program, especially when exogenous biologically active molecules are applied to maintain survival (ex: IL-2) or promote infection (ex: CD4+ T cell activation by PHA or CD3/CD28 crosslinking)." (PMID 32194526, 2020). "Non-CD4 cells, such as CD8+ T cells, DN T cells and NK cells, have been implicated in early control of severe infections with intracellular pathogens, including T. gondii, M. tuberculosis and Salmonella2,29." (PMID 32753607, 2020). "Norwegian-born MSM had the lowest estimated number of undiagnosed infections (45, using default CD4 assumptions) and undiagnosed fraction (3.6% [2.4–5.7%], using default CD4 assumptions) in 2018." (PMID 32590964, 2020).